AK2 (adenylate kinase 2)
Diseases named in the same sentence as AK2 in open-access papers (continued):
Sharing a sentence is not in itself a finding about the gene and the disease.
AK2 also shares sentences with these, for which no sentence is quoted: combined immunodeficiency (5 papers); cervical cancer (2); acute leukemia (1); acute lymphoblastic leukemia (1); colorectal cancer (1); DiGeorge syndrome (1); genetic disorder (1); Haemophilia (1); Hepatic steatosis (1); Infertility (1); Leigh syndrome (1); lung squamous cell carcinoma (1); lymphopenia (1); male infertility (1); metastatic carcinoma (1); multiple myeloma (1); Omenn syndrome (1); ovarian carcinoma (1); T cell deficiency (1); virus infection (1).